CCNB3 (cyclin B3)
Description:
Cyclins are positive regulatory subunits of the cyclin-dependent kinases (CDKs), and thereby play an essential role in the control of the cell cycle, notably via their destruction during cell division. Its tissue specificity suggest that it may be required during early meiotic prophase I.
Synonyms: CYCB3
Tractability: Small molecule: a high-quality ligand is known; it belongs to a druggable protein family. PROTAC: UniProt records ubiquitination sites on it.
Gene: Protein-coding gene on chromosome X (50,202,713 to 50,351,914, forward strand). Ensembl gene ENSG00000147082.
Subcellular location: Nucleus
Subcellular location (Human Protein Atlas): Nucleoplasm
Gene Ontology:
Molecular function: protein binding; cyclin-dependent protein serine/threonine kinase regulator activity
Cellular component: nucleoplasm; cyclin-dependent protein kinase holoenzyme complex; nucleus
Homologues: Orthologues: chimpanzee CCNB3 (99% identical), macaque CCNB3 (88% identical), dog CCNB3 (54% identical), pig CCNB3 (51% identical), guinea pig Ccnb3 (44% identical), rat Ccnb3 (35% identical), mouse Ccnb3 (34% identical), tropical clawed frog ccnb3 (16% identical), zebrafish ccnb3 (14% identical), Drosophila melanogaster CycB3 (13% identical), Caenorhabditis elegans cyb-3 (10% identical). Paralogues in human: CCNB1 (8% identical), CCNB2 (8% identical), CCNA1 (8% identical), CCNA2 (8% identical), CCNF (7% identical), CCNO (5% identical), CCNE2 (5% identical), CCNE1 (5% identical), CCNP (5% identical), CCNI2 (4% identical), CCND3 (4% identical), CCND1 (4% identical), and 6 more.
Diseases named in the same sentence as CCNB3 in open-access papers:
CCNB3 is named in the same sentence as 39 diseases in open-access papers, as found by Europe PMC text mining. Sharing a sentence is not in itself a finding about the gene and the disease. The quoted sentences say what the papers report.
sarcoma (41 papers, 2014 to 2025). A usually aggressive malignant neoplasm of the soft tissue or bone. "Heterogeneity in morphology appeared in BCOR-CCNB3 sarcomas after chemotherapy, with possible changes of immunophenotypes such as decrease or loss of expression of CCNB3 and SATB2." (PMID 35568949, 2022). "BCOR-CCNB3 sarcoma is a rare, high-grade, undifferentiated small round cell sarcoma with a specific gene fusion between the BCOR (BCL6 corepressor) and CCNB3 (Cyclin B3) genes." (PMID 40932977, 2025). "Histologically, BCOR CCNB3 sarcoma occurs typically as sheets or fascicles of spindle-to-round cells with monomorphic nuclei, subtle chromatin, and minimal cytoplasm." (PMID 40932977, 2025). "This unique combination of immunohistochemical features, along with molecular studies for BCOR and CCNB3, formed the cornerstone of BCOR-CCNB3 sarcoma diagnosis in our case." (PMID 40932977, 2025). "BCOR-rearranged sarcoma is characterized by a specific in-frame fusion of the BCOR and CCNB3 genes, its hallmark molecular change." (PMID 40932977, 2025). "BCOR alteration sarcoma includes at least three molecular subcategories: BCOR::CCNB3 fusions, BCOR-alternative non-CCNB3 partner fusions and BCOR ITD." (PMID 40948502, 2025). "BCOR is a highly sensitive marker for identifying small round cell sarcomas with BCOR gene alteration, although other reports have suggested that BCOR is less specific than CCNB3 in the diagnosis of BCOR::CCNB3 sarcomas (BCSs) and is often observed in SS." (PMID 39062853, 2024). "The “BCOR rearranged sarcoma” group consisted of BCOR::CCNB3 (n = 18), BCOR‐ITD (n = 7), YWHAE::NUTM2B (n = 3), and MAML::BCOR STS (n = 1)." (PMID 37212486, 2023). "Nine fusion genes were specific to particular histotypes, including SYT::SSX fusion in synovial sarcoma, EWSR1::FLI1 fusion in ES, EWSR1::NR4A3 fusion in EMC, BCOR::CCNB3 fusion in sarcoma with BCOR genetic alterations, and EWSR1::CREB3L1 fusion in sclerosing epithelioid fibrosarcoma." (PMID 40755265, 2025). "The ectopic expression of CCNB3 as a result of the fusion event could be the driver of oncogenesis in this novel sarcoma." (PMID 25676695, 2015). "Round cell sarcomas with BCOR alterations usually harbor BCOR::CCNB3 and BCOR::MAML3 genetic fusions, and CIC-rearranged sarcomas are characterized by CIC::DUX4 chimeric transcript." (PMID 39021466, 2024). "In contrast, the 29 patients in the “BCOR rearranged sarcoma” group were younger (p < 0.001) with a median age of 0.9 years overall (0.1–19.1) and specifically 4 years (range, 0.1–19.1) for BCOR::CCNB3 (n = 18) and 1 year (0.3–18.3) for BCOR‐ITD (n = 7)." (PMID 37212486, 2023). "The first group is characterized by sarcomas with BCOR-related gene fusions (BCOR-fusion sarcomas), most frequently BCOR::CCNB3." (PMID 36983010, 2023). "In contrast to CIC::DUX4 rearranged round cell sarcomas, BCOR::CCNB3 rearranged sarcomas are more inclined to occur in the bone, whereas CIC rearrangement sarcomas tend to develop in soft tissues and to follow a more aggressive trajectory." (PMID 38170001, 2023). "BCOR-CCNB3 sarcomas, characterized with a BCOR and CCNB3 fusion gene, are round cell undifferentiated sarcomas that share morphologic and immunohistochemical features with Ewing sarcoma (ES)." (PMID 35875106, 2022). "These discordant cases included one single BCOR‐rearranged sarcoma (with a BCOR (exon 15)‐CCNB3 (exon 5) fusion gene detected by Archer) and one single CIC‐rearranged sarcoma (with CIC rearrangement detected by FISH)." (PMID 31965673, 2020). "It is categorized into two types: BCOR-related gene fusions such as BCOR::CCNB3 sarcomas and other BCOR-rearranged sarcoma and sarcomas with internal tandem duplication of BCOR genes such as infantile undifferentiated round cell sarcomas and primitive myxoid mesenchymal tumors of infancy." (PMID 38170001, 2023).
sarcoma (continued). "Additionally, satisfactory results were obtained after the treatment of a child with a refractory pediatric sarcoma harboring paracentric inversion on the short arm of chromosome X, resulting in the fusion of the BCOR and CCNB3 genes." (PMID 36839989, 2023). "BCOR::CCNB3 sarcomas predominantly arise in bone rather than soft tissue and exhibit a higher occurrence in children and adolescent males, whereas sarcomas with BCOR internal tandem duplication show a wider age range but usually arise in the first year of life." (PMID 38170001, 2023). "Rare BCOR sarcoma was described in a group of small round cell bone tumors lacking the canonical EWSR1 translocation: only 24 BCOR::CCNB3 positive tumors could be identified in an analysis of 594 sarcoma." (PMID 37212486, 2023). "BCOR immunostain is invariably positive in most BCOR-rearranged sarcomas, including the BCOR::CCNB3, BCOR::MAML3, BCOR-ITD sarcomas, and also in certain non-BCOR-rearranged sarcomas, such as YWHAE::NUTM2B sarcomas." (PMID 40705064, 2025). "Therefore, immunohistochemistry of CCNB3 and BCOR expression may not be sufficient for diagnosis of BCOR-rearranged sarcomas." (PMID 34103053, 2021).
Ewing sarcoma (12 papers, 2016 to 2025). A small round cell tumor that lacks morphologic, immunohistochemical, and electron microscopic evidence of neuroectodermal differentiation. "Recently, approximately 4% of the Ewing sarcoma were identified as having an intrachromosomal X-fusion leading to BCOR (encoding the BCL6co-repressor) and CCNB3 (encoding the testis-specific cyclin B3)." (PMID 27453756, 2016). "Ccnb3 is a gene that has been associated with a subtype of bone sarcoma in which tumors containing a fusion between the BCL6 co-repressor (Bcor) gene and Ccnb3 gene have been shown to be distinct from Ewing sarcoma." (PMID 31013298, 2019).
Infertility (4 papers, 2013 to 2023). "In another study, a CCNB3 mutation affected the metaphase–anaphase transition in oocyte meiosis I, again leading to infertility." (PMID 35628146, 2022). "Furthermore, in female fruit fly germ cells, the absence or mutation of cyclin B3 leads to an inability to complete meiosis I and infertility, suggesting the conservation of cyclin B3′s role across species." (PMID 37686466, 2023). "If the patient is found to carry a mutation in CCNB3, her infertility may be caused by the CCNB3 mutation, and the mutation warrants more in-depth study." (PMID 37635245, 2023). "Knockout of Ccnb3 resulted in infertility in female mice due to MI arrest and overexpression of the cyclin B3 gene, which interfered with the meiosis II arrest." (PMID 37635245, 2023). "Oocytes lacking cyclin B3 maintain the metaphase I spindle and arrest at metaphase I, resulting in female mouse infertility." (PMID 37686466, 2023).
bone sarcoma (3 papers, 2019 to 2021). A sarcoma that arises from the bone. "CCNB3 can form a fusion gene with BCOR, BCOR-CCNB3, which defines a new subtype of bone sarcoma." (PMID 33719345, 2021).
breast tumors (1 paper, 2011). "Like MKI67, which encodes the proliferation-related antigen Ki-67, the expression of most of these genes (except CCNB3 and UBD) increased during the transition from grade I to ductal grade III breast tumors." (PMID 21352579, 2011).
colon cancer (1 paper, 2024). "In summary, we found that shikonin suppresses colon cancer cell proliferation and migration through cellular experiments and identified eight genes (CCNB3, IL-1α, CXCL8, CDKN2A, MYC, IGFBP3, SQSTM1, and GADD45G) associated with cell senescence through systematic bioinformatics analysis." (PMID 39188951, 2024).
female infertility (1 paper, 2023). Diminished or absent ability of a female to achieve conception. "By filtering their WES data, we identified four novel heterozygous missense mutations in the CCNB3 gene as a possible cause of female infertility." (PMID 37635245, 2023).
glioma (1 paper, 2017). A benign or malignant brain and spinal cord tumor that arises from glial cells (astrocytes, oligodendrocytes, ependymal cells). "Therefore, in the current study, the downregulation of cyclin A2, cyclin B3, and CDK1 genes could prompt cell cycle arrest in U87 glioma cells." (PMID 28837560, 2017).
metastatic tumors (1 paper, 2021). "CCNB3 was not always expressed in BCS in other studies, especially in post chemotherapeutic or metastatic tumors." (PMID 34103053, 2021).
tumor (9 papers, 2015 to 2025). "We carried out preliminary genetic characterisation by whole exome sequencing and detected tumor specific mutations in Hsp90ab1, Ccnb3 and RhoA." (PMID 31013298, 2019). "In the tumor relative to normal control tissues, the reads of the BCOR exons showed a sharp decline at the 3′ end (average: ~1000, 3′ end: ~100), and almost no read was observed in the first four exons of CCNB3." (PMID 35568949, 2022).
cancer (3 papers, 2014 to 2025). A tumor composed of atypical neoplastic, often pleomorphic cells that invade other tissues. "We removed CCNB3 due to its low expression levels among ten cancer cell lines, then the log2 fold change (CR treatment VS." (PMID 37007025, 2023).
CCNB3 also shares sentences with these, for which no sentence is quoted: synovial sarcoma (3 papers); undifferentiated sarcoma (3); and Bone Tumours (2); desmoplastic small round cell tumor (2); soft tissue tumors (2); angiomatoid fibrous histiocytoma (1); benign breast tumors (1); brain tumor (1); chondrosarcoma (1); clear cell sarcoma (1); clear cell sarcoma of the kidney (1); infantile fibrosarcoma (1); infection (1); inflammatory myofibroblastic tumor (1); liposarcoma (1); malignant melanoma (1); malignant peripheral nerve sheath tumor (1); myxoid liposarcoma (1); neuroblastoma (1); osteosarcoma (1); Pleural effusion (1); small cell sarcoma (1); Soft (1); soft tissue rhabdoid tumor (1); solitary fibrous tumor (1); spindle cell rhabdomyosarcoma (1); spindle cell tumors (1); Wilms tumours (1).